VAMP2 (vesicle associated membrane protein 2)
Description:
SNAREs (soluble N-ethylmaleimide-sensitive factor-attachment protein receptors) are essential proteins for intracellular membrane fusion. SNAREs localized on opposing membranes assemble to form a trans-SNARE complex, an extended, parallel four-helix bundle whose assembly releases energy that drives membrane fusion. The core SNARE complex typically consists of four alpha-helical domains, three from target membrane SNAREs (t-SNAREs) and one from a vesicle SNARE (v-SNARE). VAMP2 is a v-SNARE assembling into a SNARE complex with the t-SNAREs SNAP25 and STX1A to mediate the fusion of synaptic vesicles with the presynaptic plasma membrane in neurotransmitter release. Also functions in compensatory endocytosis for synaptic vesicle recycling (By similarity). In adipocytes, it is involved in the insulin-dependent exocytosis of GLUT4 storage vesicles (By similarity).
Synonyms: VAMP-2; SYB2; NEDHAHM
Tractability: Antibody: its Gene Ontology location is reachable by antibodies, with high confidence; UniProt places it where antibodies can reach, with medium confidence; UniProt predicts a signal peptide or a membrane-spanning region. PROTAC: ubiquitination databases record sites on it; its protein half-life has been measured. Other modalities: an approved drug acts on it.
Target class: Ion channel; Other ion channel; Vesicle fusion pores
Gene: Protein-coding gene on chromosome 17 (8,159,149 to 8,163,546, reverse strand). Ensembl gene ENSG00000220205.
Subcellular location: Cytoplasmic vesicle, secretory vesicle, synaptic vesicle membrane; Cell membrane
Pathways (Reactome):
Neuronal System: Acetylcholine Neurotransmitter Release Cycle; Dopamine Neurotransmitter Release Cycle; GABA synthesis, release, reuptake and degradation; Glutamate Neurotransmitter Release Cycle; Norepinephrine Neurotransmitter Release Cycle; Serotonin Neurotransmitter Release Cycle
Vesicle-mediated transport: Cargo recognition for clathrin-mediated endocytosis; Clathrin-mediated endocytosis; Golgi Associated Vesicle Biogenesis; Lysosome Vesicle Biogenesis; Translocation of SLC2A4 (GLUT4) to the plasma membrane; trans-Golgi Network Vesicle Budding
Disease: Toxicity of botulinum toxin type B (botB); Toxicity of botulinum toxin type D (botD); Toxicity of botulinum toxin type F (botF); Toxicity of botulinum toxin type G (botG); Toxicity of tetanus toxin (tetX)
Immune System: Other interleukin signaling
Metabolism: Regulation of insulin secretion
Metabolism of proteins: Insulin processing
Protein localization: Insertion of tail-anchored proteins into the endoplasmic reticulum membrane
Sensory Perception: Sensory processing of sound by inner hair cells of the cochlea
Gene Ontology:
Molecular function: protein binding; syntaxin binding; calcium-dependent protein binding; calmodulin binding; phospholipid binding; SNAP receptor activity; SNARE binding; syntaxin-1 binding
Biological process: eosinophil degranulation; mucus secretion; natural killer cell degranulation; neutrophil degranulation; protein transport; regulation of histamine secretion by mast cell; vesicle fusion; calcium-ion regulated exocytosis; cellular response to insulin stimulus; exocytosis; Golgi to plasma membrane protein transport; long-term synaptic potentiation; membrane fusion; neurotransmitter secretion; positive regulation of intracellular protein transport; protein-containing complex assembly; regulation of delayed rectifier potassium channel activity; regulation of exocytosis; regulation of vesicle-mediated transport; response to glucose; SNARE complex assembly; synaptic vesicle endocytosis; synaptic vesicle exocytosis; vesicle-mediated transport
Cellular component: clathrin-coated vesicle; membrane; secretory granule membrane; SNARE complex; synaptobrevin 2-SNAP-25-syntaxin-1a complex; vesicle; clathrin-coated endocytic vesicle membrane; clathrin-sculpted gamma-aminobutyric acid transport vesicle membrane; clathrin-sculpted glutamate transport vesicle membrane; clathrin-sculpted monoamine transport vesicle membrane; cytoplasmic vesicle; cytosol; neuron projection; neuron projection terminus; perinuclear region of cytoplasm; plasma membrane; presynaptic membrane; secretory granule; synapse; synaptic vesicle; synaptic vesicle membrane; synaptobrevin 2-SNAP-25-syntaxin-1a-complexin I complex; synaptobrevin 2-SNAP-25-syntaxin-1a-complexin II complex; trans-Golgi network; voltage-gated potassium channel complex; and 2 more
Genetic constraint (gnomAD): Loss-of-function variants: 0 observed, 16.93 expected, observed/expected ratio (o/e) 0, 90% interval 0 to 0.18. The upper end of that interval is the gene's LOEUF score, 0.18, which puts it in group 1 of 6, group 1 being the genes least tolerant of losing a copy. Missense variants: 95 observed, 154.46 expected, observed/expected ratio (o/e) 0.62, 90% interval 0.52 to 0.73. Synonymous variants: 67 observed, 61.3 expected, observed/expected ratio (o/e) 1.09, 90% interval 0.9 to 1.34.
Homologues: Orthologues: chimpanzee VAMP2 (99% identical), guinea pig VAMP2 (99% identical), dog VAMP2 (98% identical), mouse Vamp2 (96% identical), pig VAMP2 (96% identical), rat Vamp2 (96% identical), tropical clawed frog vamp2 (89% identical), Caenorhabditis elegans snb-1 (64% identical). Paralogues in human: VAMP1 (81% identical), VAMP3 (63% identical), VAMP7 (36% identical), VAMP4 (30% identical), VAMP5 (30% identical), VAMP8 (27% identical), YKT6 (23% identical), SEC22B (22% identical), SEC22C (19% identical), SEC22A (16% identical).
Diseases named in the same sentence as VAMP2 in open-access papers:
VAMP2 is named in the same sentence as 86 diseases in open-access papers, as found by Europe PMC text mining. Sharing a sentence is not in itself a finding about the gene and the disease. The quoted sentences say what the papers report.
epilepsy (11 papers, 2019 to 2025). A brain disorder characterized by episodes of abnormally increased neuronal discharge resulting in transient episodes of sensory or motor neurological dysfunction, or psychic dysfunction. "In the context of VAMP2 pathogenic variants, impaired vesicle fusion, and neurotransmitter release are central to the pathophysiology of epilepsy in these patients, leading to a cascade of abnormal neuronal activity that manifests as seizures." (PMID 39596051, 2024). "Studies have shown that some diseases of nervous system development, including epilepsy and abnormal movement, are caused by VAMP2 gene mutation, which mainly leads to the impairment of presynaptic nerve transmission at nerve terminals." (PMID 36618823, 2022). "Pathogenic variants of VAMP2 gene are associated with neurodevelopmental disorders, such as visual impairment, hyperkinetic movements, autism spectrum disorder and epilepsy." (PMID 35350397, 2022). "Off-label treatment with 4-AP also improved the clinical outcome of one patient affected by vesicle-associated membrane protein 2 (VAMP2)-related epilepsy through increased exocytosis and improved GABAergic tone." (PMID 34576077, 2021). "VAMP2 (vesicle-associated membrane protein 2): 2/5 patients had hyperkinetic MD and epilepsy, with neonatal-onset in one." (PMID 33919646, 2021). "For instance, patients with VAMP2 pathogenic variants showed a neurodevelopmental disorder characterized by ID, central visual impairment, movement disorders, epilepsy or electroencephalographic abnormalities, autistic features, and loss of purposeful hand movements resembling Rett syndrome." (PMID 35350397, 2022). "This highlights the significant impact of VAMP2 dysfunction on synaptic transmission, which can lead to more severe forms of epilepsy characterized by frequent and often drug-resistant seizures." (PMID 39596051, 2024). "In line with our findings, VAMP2 expression was found to be reduced in animal models or patients' brain tissues of Parkinson, epilepsy, and dementia." (PMID 37380951, 2023). "The importance of a correct mechanism of neuronal trafficking mediated by Vamp2 has been highlighted by a recent study evaluating the essential role of VAMP2 and DLG4 in the progression of epilepsy and behavioral disorders, in particular ADHD." (PMID 35350397, 2022).
diabetes (9 papers, 2009 to 2024). "The experimental results showed that the protein level of VAMP2 was elevated in the kidney tissues of patients with diabetes and hypertension." (PMID 36675205, 2023). "In animals with diabetes induced by streptozotocin and nicotinamide, resveratrol supplementation increased the VAMP2 gene expression and blood insulin level, as well as reduced the fasting blood glucose and improved the insulin resistance." (PMID 28812028, 2017). "VAMP2 and Cdc42 localize together at the plasma membrane and on insulin secretory granules in β-cells and play vital functions in insulin secretion and development of diabetes." (PMID 34394002, 2021). "However, other genes such Vamp2, Chi3l3 and Shc1 were both significantly overexpressed in mice developing diabetes late and expression correlated with time of diabetes onset (correlation coefficients 0.841, 0.681 and 0.718; P-values 0.004, 0.035 and 0.024, respectively)." (PMID 26366287, 2015). "The presynaptic proteins synaptophysin, synapsin 1, VAMP2, SNAP25, and PSD95 all show decreases after only one month of diabetes, especially when synaptosomal fractions are selectively examined." (PMID 19936028, 2009). "Two genes, Vamp2 and Chi3l3, were not significantly differentially expressed in mice according to diabetes onset before or after 17 weeks of age (data not shown)." (PMID 26366287, 2015).
Insulin resistance (7 papers, 2012 to 2023). Increased resistance towards insulin, that is, diminished effectiveness of insulin in reducing blood glucose levels. "In this study, we bioinformatically focused on miR-135 and two predicted target genes, insulin receptor (Insr) and vesicle associated membrane protein 2 (Vamp2) as the first components in the cascade causing insulin resistance in cells." (PMID 27602317, 2016). "Furthermore, VAMP2, which belongs to the SNAP receptor protein family (SNARE) and has been associated with insulin resistance in T2DM, was underrepresented in PTDM." (PMID 37626301, 2023). "Taken together, our results revealed SLN-RES could be a modern and interestingly therapeutic approach for the improvement of insulin resistance through targeting the expression of Snap23, Stx4, and Vamp2 in adipose and muscle tissues." (PMID 31290033, 2019). "Defects in insulin-stimulated GLUT4 translocation during insulin resistance can be due to impaired sorting of GLUT4 into the GSVs and the downregulation of regulatory proteins of GSV trafficking, such as VAMP2 and sortilin." (PMID 37229459, 2023). "We have examined Vamp2 and Insr expressions in transfected C2C12 cells, to identify potential markers within development of insulin resistance." (PMID 27602317, 2016).
liver cancer (7 papers, 2020 to 2026). An epithelial or non-epithelial malignant neoplasm that arises from the liver. "In the HULC/miR-383-5p/VAMP2 axis, the expression of lncRNA was highly upregulated in liver cancer (HULC), and the expression of vesicle-associated membrane protein-2 (VAMP2) was enhanced, whereas miR-383-5p was downregulated in HCC tissues." (PMID 36313570, 2022). "VAMP2 acts as a downstream target and plays a pro-tumorigenic role in liver cancer." (PMID 36248974, 2022).
Alzheimer disease (6 papers, 2021 to 2025). A progressive, neurodegenerative disease characterized by loss of function and death of nerve cells in several areas of the brain leading to loss of cognitive function such as memory and language. "The APOE genotype, a significant genetic risk factor of Alzheimer’s disease, has been shown to interact with VAMP2." (PMID 40003632, 2025). "This selection was made to scrutinize the influence of the APOE genotype on the modulation of the VAMP2/SYNTAXIN1/SNAP25 protein complex system within the brains of individuals with Alzheimer’s disease." (PMID 40003632, 2025). "In conclusion, plasma levels of glial fibrillary acidic protein and vesicle-associated membrane protein 2 may reflect synapse pathology independent of age and beyond general neuronal loss, even in absence of detectable Alzheimer’s disease pathology." (PMID 40620474, 2025). "Through co-expression modular analysis, we identified that the genes diminished in Alzheimer’s disease are most enriched in module 1 (M1) that contains SNARE-binding complex genes, including the core SNARE genes, SNAP-25, STX1A and VAMP2." (PMID 34423299, 2021). "In conclusion, the present study delved into the effects of APOE4 on the VAMP2/SYNTAXIN1/SNAP25 complex through molecular dynamics simulations, revealing the mechanism by which it may contribute to early synaptic dysfunction in Alzheimer’s disease (AD)." (PMID 40003632, 2025). "Importantly, these associations were observed in absence of Alzheimer’s disease pathology and beyond GM loss, suggesting that plasma levels of VAMP2 and GFAP may reflect early synaptic alterations, not specific to Alzheimer’s disease and prior to substantial neurodegeneration." (PMID 40620474, 2025). "Many of the SNARE complex genes involved in presynaptic vesicle exocytosis were significantly downregulated in Alzheimer’s disease, including SNAP-25, STX1A, SYT1 and VAMP2, while STX2, SYN1 and VAMP3 were not changed." (PMID 34423299, 2021).
Intellectual disability (6 papers, 2019 to 2025). "Here, we report five heterozygous de novo mutations in VAMP2 in unrelated individuals presenting with a neurodevelopmental disorder characterized by axial hypotonia (which had been present since birth), intellectual disability, and autistic features." (PMID 30929742, 2019). "For example, USP9X and VAMP2 play critical roles in intellectual disability and autism diseases, respectively." (PMID 35794099, 2022).
Parkinson disease (6 papers, 2009 to 2025). A progressive degenerative disorder of the central nervous system characterized by loss of dopamine producing neurons in the substantia nigra and the presence of Lewy bodies in the substantia nigra and locus coeruleus. "Differentially expressed proteins such as PARK7 (DJ-1), VAMP2, and proteasome subunits are well-documented in the Parkinson’s disease literature, and their identification reinforces the biological plausibility of the observed alterations." (PMID 40725009, 2025). "Similarly, α-Synuclein, another Parkinson's disease protein, alters neurotransmitter release by preventing the v-SNARE vesicle-associated membrane protein (VAMP)-2, also known as Synaptobrevin-2, from joining the SNARE complex cycle." (PMID 33581113, 2021).
neuroblastoma (5 papers, 2009 to 2025). Neuroblastoma (NB) is the most common solid, extracranial childhood tumor. "Wild-type human full-length SNCA and VAMP2, encoding aSyn and VAMP2, were cloned from cDNA obtained from human neuroblastoma cells (SH-SY5Y) and inserted into the pEYFP-N1 and pMD2.G vector (Addgene #96,808, #12,259) with a C-terminal YFP and Flag-tag, respectively." (PMID 41013605, 2025). "A study in 2018 analyzed human neuroblastoma SH-S5Y5 cells and found that both DA-induced oligomeric α-synuclein aggregates and α-synuclein PPFs lead to sequestered levels of VAMP-2." (PMID 36139038, 2022).
type 2 diabetes mellitus (5 papers, 2014 to 2021). A type of diabetes mellitus that is characterized by insulin resistance or desensitization and increased blood glucose levels. "Moreover, VAMP-2 and Syntaxin-1 are strongly diminished in pancreatic islets isolated from Type 2 diabetic patients." (PMID 24503905, 2014).
Cognitive impairment (4 papers, 2015 to 2025). Abnormal cognition is characterized by deficits in thinking, reasoning, or remembering. "In the present paper we studied VAMP2 gene expression and VAMP2 26 bp polymorphism distribution in a cohort of elderly persons with different forms of cognitive impairment and dementia." (PMID 35360211, 2022). "The VAMP2 mRNA expression level obtained from available PBMCs of 438 subjects out of the 674 enrolled were next evaluated according to cognitive impairment (73 AD, 122 MD, 140 CT and 103 MCI of which 18 MCI-MD and 19 MCI-AD)." (PMID 35360211, 2022). "Considering the crucial role of VAMP2 in the SNARE complex assembly, we evaluated whether VAMP2 could be a novel peripheral biomarker that can distinguish among different forms of cognitive impairment in old persons." (PMID 35360211, 2022). "We evaluated ApoE4 and VAMP2 26 bp Ins/Del genotype distribution in 177 AD, 132 MD, 115 Mild Cognitive Impairment (MCI) and 250 individuals without cognitive decline (CT), as well as VAMP2 gene expression in a subset of 73 AD, 122 MD, 103 MCI and 140 CT." (PMID 35360211, 2022). "Expression of VAMP2, Syntaxin1, and SNAP-25 is reduced in human AD brain samples, and intracellular Aβ oligomers have been shown to bind to SNARE proteins and thereby inhibit the SNARE complex formation, blocking neurotransmission and exacerbating cognitive defects." (PMID 39773760, 2025).
dementia (4 papers, 2021 to 2025). Loss of intellectual abilities interfering with an individual's social and occupational functions. "Longitudinal studies and analyses focusing on the impact of the 26 bp Ins/Del variant on VAMP2 gene and protein expression will also shed more light on the role of VAMP2 in the pathogenesis of dementia." (PMID 35360211, 2022). "Receiver operating characteristic curve analysis was employed to evaluate the ability of VAMP2 gene expression to discriminate between clinically different forms of dementia." (PMID 35360211, 2022). "In addition to VAMP2, we also observed associations of GFAP with synaptic density, yet now within structures typically involved in dementia, such as the precuneus, cingulate gyrus and parahippocampus." (PMID 40620474, 2025). "This higher frequency of VAMP2 26 bp Del among the MD patients may account for the higher VAMP2 mRNA expression seen in mixed form of dementia." (PMID 35360211, 2022). "The current study demonstrates that elevated plasma levels of VAMP2 as well as GFAP correspond to lower synaptic density within distinct regions in the brains of older adults without dementia." (PMID 40620474, 2025). "VAMP2 involvement, both at mRNA and protein levels, in the pathogenesis of VAD and in different forms of well-defined dementia, indeed suggest a possible role for this gene in the vascular alteration seen in the mixed form of dementia, that will need to be further investigated." (PMID 35360211, 2022). "We aimed to answer these questions by examining whether blood-based levels of VAMP2 and SNAP25 along with blood-based ATN(I) biomarkers are associated with SV2A PET in the brains of older adults without dementia." (PMID 40620474, 2025). "Finally, a reduction of Synaptophysin, a presynaptic protein that binds VAMP2 and plays a role in SNARE complex assembly and vesicle fusion, was observed to be present in FTD patients, suggesting a fundamental role of synaptic decline in dementia." (PMID 35360211, 2022). "Although being preliminary, these results strongly suggest that VAMP2 mRNA expression is a possible early indicator able to distinguish MCI evolution to MD or AD as reinforced by the ROC evaluation and reinforce the hypothesis that VAMP2 is a crucial gene in mixed form of dementia, but not in AD." (PMID 35360211, 2022).